SNORD126 (small nucleolar RNA, C/D box 126)
Synonyms: hsa-mir-1201; formerly MIR1201; MIRN1201
Gene: Small nucleolar RNA gene on chromosome 14 (20,326,450 to 20,326,526, reverse strand). Ensembl gene ENSG00000238344.
Gene Ontology:
Biological process: RNA processing
Cellular component: nucleolus
Homologues: Orthologues: chimpanzee SNORD126 (100% identical), macaque SNORD126 (100% identical), rabbit SNORD126 (95% identical), rat LOC120097276 (90% identical), pig SNORD126 (84% identical).
Diseases named in the same sentence as SNORD126 in open-access papers:
SNORD126 is named in the same sentence as 9 diseases in open-access papers, as found by Europe PMC text mining. Sharing a sentence is not in itself a finding about the gene and the disease. The quoted sentences say what the papers report.
hepatocellular carcinoma (4 papers, 2020 to 2021). A malignant tumor that arises from hepatocytes. "For instance, SNORD126 was found highly expressed in colorectal cancer and hepatocellular carcinoma and further associated with tumor stage in the latter." (PMID 33125686, 2021).
colorectal cancer (2 papers, 2021). A primary or metastatic malignant neoplasm that affects the colon or rectum. "In our previous work, we demonstrated that snoRD126 promotes the progression of hepatocellular and colorectal cancer by upregulating FGFR2 to activate the PI3K-AKT pathway." (PMID 33891563, 2021).
alcohol steatohepatitis (1 paper, 2024). "According to these studies, we selected four snoRNAs (snoRA12, snoRA47, snoRA80E, and snoRD126) for exploration in the context of non-viral-related causes, including non-alcoholic steatohepatitis (NASH), non-alcoholic fatty liver diseases (NAFLD), and alcohol steatohepatitis." (PMID 39022679, 2024).
liver cancer (1 paper, 2021). An epithelial or non-epithelial malignant neoplasm that arises from the liver. "First, we examined the expression levels of snoRD126 in a panel of liver cancer cell lines and the normal human hepatocyte line 7702." (PMID 33891563, 2021). "In this study, we found that snoRD126 binds to hnRNPK and regulates FGFR2 expression, promoting the development of liver cancer." (PMID 33891563, 2021).
ovarian carcinoma (1 paper, 2022). A malignant neoplasm originating from the surface ovarian epithelium. "In addition, plate clone formation assay showed that overexpression of snoRD126 and snoRD89 significantly increased the number of clone formation in ovarian cancer cells, and the size was larger in OE group." (PMID 35187852, 2022). "Therefore, we speculate that snoRD89 and snoRD126 may affect the prognosis of ovarian cancer by regulating the stem of ovarian cancer cells." (PMID 35187852, 2022).
viral infection (1 paper, 2020). "The mutant transcript significantly abolished the promoting effect of the wild-type transcript on viral infection with respect to both viral RNA levels and protein expression, further demonstrating that the functions of SNORD126 on HCV infection are snoRNP dependent." (PMID 33042070, 2020).
tumor (4 papers, 2021 to 2024). "SnoRA12, snoRA47, snoRA80E, and snoRD126 were studied by quantitative real-time PCR (qRT-PCR) in tumor and non-tumor adjacent tissue (NTAT) samples." (PMID 39022679, 2024). "Indeed, in tumours compared with non-tumour tissues, it has been found a down-regulation of SNORD113–1 associated with worse survival, and an up-regulation of SNORA47, SNORD126, SNORD78 and SNORD76 linked to the aggressive phenotype and poor prognosis of HCC." (PMID 35331312, 2022).
cancer (1 paper, 2021). A tumor composed of atypical neoplastic, often pleomorphic cells that invade other tissues. "Importantly, we identified the critical domain of snoRD126 responsible for its cancer-promoting functions." (PMID 33891563, 2021). "Importantly, we identified the critical domains of snoRD126 that mediate its cancer-promoting effects." (PMID 33891563, 2021).
SNORD126 also shares sentences with these, for which no sentence is quoted: non-alcoholic fatty liver diseases (1 paper).